PPP3CA-DT (PPP3CA divergent transcript)
Synonyms: FLJ20021; SRSP; FLJ
Gene: Long non-coding RNA gene on chromosome 4 (101,347,733 to 101,349,436, forward strand). Ensembl gene ENSG00000254531.
Diseases named in the same sentence as PPP3CA-DT in open-access papers:
PPP3CA-DT is named in the same sentence as 7 diseases in open-access papers, as found by Europe PMC text mining. Sharing a sentence is not in itself a finding about the gene and the disease.
PPP3CA-DT shares sentences with these, for which no sentence is quoted: colorectal cancer (4 papers); cancer (3); laryngeal carcinoma (2); tumor (2); head and neck cancer (1); lymph node metastasis (1); nasopharyngeal carcinoma (1).